EFNB2 (ephrin B2)
Diseases named in the same sentence as EFNB2 in open-access papers (continued):
Sharing a sentence is not in itself a finding about the gene and the disease.
melanoma (13 papers, 2005 to 2022). A malignant, usually aggressive tumor composed of atypical, neoplastic melanocytes. "In an experimental melanoma metastasis model, Ephrin-B2–EphB4 interaction prevents the metastatic dissemination of melanoma cells after retrograde carotid artery injection by inducing melanoma cell repulsion from bone endothelial cells." (PMID 34360793, 2021). "In conclusion, the Ephrin-B2–EphB4 pathway is primarily involved in mediating tumor-endothelial cell interactions during metastatic dissemination of circulating melanoma cells." (PMID 34360793, 2021). "Here, we demonstrate that the effects of the Ephrin-B2–EphB4 interaction on the metastatic dissemination of circulating melanoma cells depend on intact forward and reverse signaling." (PMID 34360793, 2021). "EphB4 stimulation during tumor cell seeding led to an increase in spinal metastatic loci and number of disseminated melanoma cells, as well as earlier locomotion deficits in the presence of endothelial Ephrin-B2." (PMID 34360793, 2021). "It seems that Ephrin-B2-Fc exerts only minor effects when melanoma cells have reached the metastatic niche and are developing into a solid lesion." (PMID 34360793, 2021). "The soluble EphB4-stimulating ligand Ephrin-B2-Fc or the EphB4 RTK inhibitor NVP-BHG 712 were applied during the hematogenous dissemination of metastatic melanoma cells." (PMID 34360793, 2021). "PEGylated TNYL-RAW inhibits EphB4 phosphorylation in melanoma cells stimulated with ephrin-B2 even 24 hours after its addition to cell culture medium, whereas the less stable unmodified TNYL-RAW is ineffective after prolonged incubation in cell culture medium." (PMID 22194865, 2011). "EphB4-ephrin-B2 bidirectional signaling appears to promote the malignancy of certain cancers, such as melanoma." (PMID 22194865, 2011). "Interrupted reverse signaling to endothelial cells may translate into increased adhesion of melanoma cells to bone endothelium comparable to observations under endothelial Ephrin-B2 depletion." (PMID 34360793, 2021). "Inhibition of EphB4-ephrin-B2 interaction by PEG-TNYL-RAW could also be useful to inhibit the growth of cancer cells in which EphB4-ephrin-B2 interaction promotes tumorigenesis, such as melanoma cells." (PMID 22194865, 2011). "Consistent with increased stability, submicromolar concentrations of PEGylated TNYL-RAW effectively impair EphB4 activation by ephrin-B2 in cultured B16 melanoma cells as well as capillary-like tube formation and capillary sprouting in co-cultures of endothelial and epicardial mesothelial cells." (PMID 22194865, 2011). "Therefore, it was the aim to further elucidate the modulation of the metastatic capability by the Ephrin-B2–EphB4 pathway in a ligand-dependent and ligand-independent retrograde carotid artery injection melanoma metastasis model and to validate its potential for future therapeutic strategies." (PMID 34360793, 2021). "A direct role for EphB4 in tumour angiogenesis has been suggested by experiments showing that A375 melanomas form smaller tumours in the presence of soluble EphB4 possibly because the soluble EphB4 interferes with binding of endogenous EphB4 on tumour cells to ephrin-B2 on endothelial cells." (PMID 16171530, 2005).
colon carcinoma (10 papers, 2004 to 2024). "We transfected the full-length ephrin-B2 cDNA into the human colon cancer cell line KM12L4 and found that the in vivo growth of ephrin-B2-overexpressing tumours was significantly decreased compared to control tumours." (PMID 15083195, 2004). "We conclude that overexpression of ephrin-B2 suppresses tumour cell growth and vascular function in this in vivo colon cancer model." (PMID 15083195, 2004). "We found that overexpression of ephrin-B2 in colon cancer cells did lead to an increase in tumour angiogenesis, but that these vessels were not functional." (PMID 15083195, 2004). "The first was that overexpression of ephrin-B2 on tumour cells can markedly decrease the growth of SQ colon cancer xenografts." (PMID 15083195, 2004). "Initial reports concerning the expression of EPHB2, EPHB3, EPHB4, and ephrin-B2 mRNA document significant alterations in the expression patterns among cancerous colonic cancer cells lines, surgical specimens, and the contiguous healthy tissue, with ephrin-B2 being the most variably expressed." (PMID 35269901, 2022). "To investigate this hypothesis, we stably transfected KM12L4 human colon cancer cells with ephrin-B2 to study its effect on tumour growth in vivo." (PMID 15083195, 2004). "As the Eph/ephrin system is involved in embryologic vasculogenesis and ephrin-B2 is expressed ubiquitously in all colon cancers studied in our laboratory, we hypothesised that overexpression of ephrin-B2 in colon cancer cells may induce tumour angiogenesis and increase tumour growth." (PMID 15083195, 2004). "With two widely used colon cancer cell lines, COLO205 and HCT116, we found upregulation of ephrin-B2 by flow cytometry using EC8." (PMID 22292016, 2012). "Northern blotting was performed to determine the frequency of expression of ephrin-B2 and EphB4 in human nonmalignant cell lines and colon cancer cell lines." (PMID 15083195, 2004). "When colon tumor tissues were immunostained after tumor growth in mice and harvest, EC8 not only delineated human tumor xenograft with high ephrin-B2 expression, but also identified the vasculature within the tumor due to the cross-reactivity of EC8 with both human and murine ephrin-B2." (PMID 22292016, 2012).
prostate carcinoma (8 papers, 2015 to 2025). A carcinoma that arises from epithelial cells of the prostate gland. "Among surgically resected 74 prostate cancers and 16 normal prostate tissues, ephrin-B2 was induced in 58% (43 out of 74) of the prostate tumors while normal prostate glands showed no expression." (PMID 40044981, 2025). "PTEN deletion induces EphB4 and ephrin-B2 in prostate cancer which was substantially reduced when EPHB4 is deleted in the same prostate epithelial cells." (PMID 40044981, 2025). "Prostate cancer cells were demonstrated to interact with stromal cells expressing ephrin-B2 in human prostate cancer tissues." (PMID 38730588, 2024). "Collectively, our results show that inhibition of the EPHB4 receptor or its ligand EFNB2 decreases cell viability and induces apoptosis in prostate cancer cells." (PMID 31641103, 2019). "Thus EphB4-ephrin-B2 pathway has sustained role from initiation to progression in prostate cancer including androgen independence." (PMID 40044981, 2025). "PI3K pathway activation is a common and early event in prostate cancer, from loss of function mutations in PTEN, or activating mutations in PIK3Ca or AKT leading to constitutive activation, induction of growth factor-receptors kinase EphB4 and its ligand ephrin-B2." (PMID 40044981, 2025). "NR2F2 (COUP-TFII) plays a critical role in mediating the effects of DHA treatment on EFNB2, EBF1, ETS1, and VEGFA expression, and the knockdown of NR2F2 can recede the functional changes induced by DHA treatment in prostate cancer cells." (PMID 39364872, 2025). "ephrin-B2 expression did not correlate with Gleason grade, or tumor stage in this small study of resectable prostate cancers, while ephrin-B2 induction begins early in the disease." (PMID 40044981, 2025).
endometrial cancer (7 papers, 2008 to 2025). Primary or metastatic malignant neoplasm involving the endometrium (mucous membrane that lines the endometrial cavity). "Ephrin-B2 is also highly expressed in endometrial cancer, and patients with low ephrin-B2 expression have a better prognosis." (PMID 35126464, 2021). "Several reports have examined concomitant expression of the ligand EFNB2 and its receptor EphB4 in leukemia-lymphoma cell lines, and in endometrial cancer." (PMID 21333016, 2011). "In endometrial carcinomas, Ephrin-B2 (EFNB2) expression may reflect or induce increased potential for growth and tumorigenicity." (PMID 22203846, 2011). "Our transcriptome assay uncovered that Ephrin-B2 (EFNB2) and Pre-B cell leukaemia homobox-1 (PBX1) were the two recurrently downregulated DEGs in sfTSLP-expressing ovarian and endometrial cancer cells." (PMID 33652749, 2021). "We further investigated the impact of sfTSLP overexpression on transcriptome by RNA-sequencing and found that EFNB2 and PBX1 were downregulated in ovarian and endometrial cancer cells, suggesting their role in sfTSLP-mediated tumour growth." (PMID 33652749, 2021).
neuroblastoma (7 papers, 2013 to 2024). Neuroblastoma (NB) is the most common solid, extracranial childhood tumor. "In their first study, they identified the expression of EPHB6, ephrin-B2, and ephrin-B3 in neuroblastoma cells, correlating with a favorable prognosis." (PMID 38612645, 2024). "In neuroblastoma, high expression of EFNB2 has been reported to predict favorable outcomes." (PMID 37958393, 2023). "Increases in favorable neuroblastoma genes, EFNB2, MIZ-1, and TrkA, were also observed." (PMID 36185250, 2022). "Among the favorable neuroblastoma genes examined (EPHB6, EFNB2, EFNB3, TrkA, CD44, MIZ-1), S(+)-ibuprofen augmented the expression of EPHB6 significantly in four of five neuroblastoma cell lines tested." (PMID 24173829, 2014).
pancreatic ductal adenocarcinoma (7 papers, 2020 to 2024). An infiltrating adenocarcinoma that arises from the epithelial cells of the pancreas. "EFNB2 gene expression, fostering cellular proliferation, migration, and invasive tendencies particularly in pancreatic ductal adenocarcinoma, emerges as both a biological compass and a prognostic touchstone in a plethora of malignancies." (PMID 37796226, 2023). "EFNB2 acts as a oncogene in pancreatic ductal adenocarcinoma (PDAC) and is markedly upregulated in PDAC and correlated to clinical stage and Ki67 expression levels in PDAC." (PMID 33648511, 2021). "EFNB2 is another essential protein that is overexpressed in pancreatic ductal adenocarcinoma." (PMID 35646067, 2022).
myocardial infarction (6 papers, 2019 to 2025). Gross necrosis of the myocardium, as a result of interruption of the blood supply to the area, as in coronary thrombosis. "Some individual genes of this fraction could serve as valuable biomarkers: Efnb2 was found to be highly expressed after myocardial infarction in vivo." (PMID 32573098, 2020).
ovarian carcinoma (6 papers, 2008 to 2026). A malignant neoplasm originating from the surface ovarian epithelium. "Subsequently, the remaining prognostic biomarkers from other cancer types were also assessed by OSov, which demonstrated that these genes (SFRP4, NUAK1, MFAP2, PLIN1 and EFNB2) exhibited good performance in predicting ovarian cancer patient outcome." (PMID 35053021, 2021). "mRNA expression of EFNB2 and PBX1 in IOSE, FTSEC and human ovarian cancer cell lines were also analysed by qRT-PCR." (PMID 33652749, 2021). "Moreover, four neural genes (NTN1, UNC5B, EFNB2, and EFNA5) were nominated as promising biomarkers and therapeutic targets in ovarian cancer patients." (PMID 39456618, 2024).
diabetes (5 papers, 2015 to 2025). "In the current study, we tested the hypothesis that diabetes causes an increase in Ephrin-B2 expression in pericytes that contributed to diabetes-mediated pathological cerebral neovascularization." (PMID 30620753, 2019). "Our findings introduce Ephrin-B2 signaling as a promising therapeutic target to improve cerebrovascular integrity in diabetes." (PMID 30620753, 2019). "The purpose of the current study is to unravel the role of Ephrin-B2 signaling in pericytes as one of the signaling mechanisms that is involved in diabetes-mediated pathological cerebrovascular neovascularization." (PMID 30620753, 2019). "Yet, how diabetes alters Ephrin-B2 expression in pericytes in cerebrovasculature is a gap in our knowledge." (PMID 30620753, 2019). "On the other hand, we showed that silencing Ephrin-B2 in pericytes decreased diabetes-induced angiogenic properties as seen in decreased pericyte migration and pericyte/endothelial cell co-culture reduced tube formation." (PMID 30620753, 2019). "Altogether, our findings emphasize the crucial role of pericytes in the pathological neovascularization in diabetes and establish Ephrin-B2 signaling as a potential target to improve cerebrovascular integrity in diabetes." (PMID 30620753, 2019). "Our data showed that selective inhibition of Ephrin-B2 in pericytes significantly decreased the diabetes-induced cerebral pathological neovascularization indices." (PMID 30620753, 2019). "We show that diabetes enhances Ephrin-B2 in pericytes which disturbs pericyte/endothelial interaction and increases cerebral neovascularization." (PMID 30620753, 2019). "Culturing human brain microvascular pericytes in diabetes-mimicking conditions (high glucose and palmitate) increased Ephrin-B2 expression and activity." (PMID 30620753, 2019). "Our results showed that diabetes-induced pathological cerebral neovascularization was accompanied with an increased Ephrin-B2 expression in the diabetic rat cerebrovasculature compared to control." (PMID 30620753, 2019). "In addition, our findings greatly accentuate Ephrin-B2 signaling as a promising therapeutic target to improve cerebrovascular integrity in diabetes." (PMID 30620753, 2019). "Diabetes increased the expression of Ephrin-B2 in the cerebrovasculature and pericytes." (PMID 30620753, 2019). "Taken all together, in this study we hypothesize that pericytes play a crucial role in diabetes-mediated pathological cerebral neovascularization via dysregulation of Ephrin-B2 signaling." (PMID 30620753, 2019). "In the present study, we tested the hypothesis that the increased proangiogenic Ephrin-B2 signaling in PCs contributes to the dysfunctional cerebral neovascularization in diabetes." (PMID 30620753, 2019). "In addition, diabetes has been found to increase the expression of Ephrin-B2 in cerebral blood vessels and pericytes and increase cerebral neovascularization, which may be related to impaired cognitive function in diabetic patients." (PMID 40313483, 2025). "Yet, how diabetes alters Ephrin-B2 expression in pericytes in the cerebrovasculature is unknown." (PMID 30620753, 2019). "DM significantly increases Ephrin-B2 expression in diabetic retina and HRP, increasing Ephrin-B2 signaling in the pericytes, and leading to inflammation and apoptosis in retinal vessels." (PMID 38027131, 2023). "Then, our study extends these findings by establishing that endothelial MPs carrying miR-503 interfere with EFNB2 and VEGFA expression in pericytes, further blocking post-ischaemic angiogenesis and vascular integrity under diabetes." (PMID 26268439, 2015).
encephalitis (5 papers, 2009 to 2024). An acute inflammatory process affecting the brain parenchyma. "NiV ephrin B2 and B3 receptors are expressed on neural cells and the wild-type NiV is neurotropic and causes encephalitis in affected patients." (PMID 35759511, 2022). "In particular, the NiV G protein is a ligand for ephrin B2 and ephrin B3 receptors expressed on neurons and is believed to play a role in neurotropism and encephalitis in human NiV disease." (PMID 35759511, 2022). "It is thought that ephrin B3 binding is a prerequisite for encephalitis in humans and other mammals because it is expressed by cells of the brain stem, whereas ephrin B2 is principally found on other cells, including endothelial cells." (PMID 30909389, 2019). "EFNB2 is likely the key receptor for Nipah virus for transmission, while EFNB3-mediated infection may contribute to the fatal encephalitis and brain pathology frequently observed in human infections." (PMID 38659959, 2024).
hepatocellular carcinoma (5 papers, 2017 to 2024). A malignant tumor that arises from hepatocytes. "Erythropoietin-producing human hepatocellular carcinoma (ephrin) receptors like Ephrin B2 are expressed by ECs and EPCs, and they are important for embryonic angiogenesis, cellular adhesion, and migration." (PMID 33627177, 2021). "Here, we examined the expression of EFNB2 in liver cell carcinoma specimens by using RNA‐Seq data from 292 paired tumour and adjacent normal samples obtained from The Cancer Genome Atlas." (PMID 30589500, 2018).
lung carcinoma (5 papers, 2013 to 2024). "The stimulatory effects of BaP on angiogenic and tumorigenic genes including Clec14a, Efnb2, Id1, and Junb were higher in males than in females, which is consistent with the finding that the male sex is a significant risk factor for lung cancer in SLE patients, especially among smokers." (PMID 37047136, 2023). "To examine whether EphA3 can also be regulated by cis interaction with ephrin-B2, we infected A549 lung cancer cells expressing EphA3 with lentiviruses encoding EGFP-ephrin-B2 or only EGFP as a control." (PMID 24348920, 2013). "This includes genes involved in cancer progression such as Kif26a, Acer2, Serpine1, Nr1d2, Efnb2 as well as Chst11, which have all previously been shown to be deregulated in various forms of cancer, including lung cancer." (PMID 39273313, 2024). "On the contrast, Ephrin-B2, a transmembrane ligand for EphB1 forward signaling, inhibited migration and invasion of lung cancer cells." (PMID 32368295, 2020). "We indeed found that ephrin-A3 overexpressed in lung cancer cells can inhibit EphA2 and EphA3 activation by ephrins in trans while overexpression of ephrin-B2 can inhibit activation of EphA3 and EphB4." (PMID 24348920, 2013).
pancreatic cancer (5 papers, 2021 to 2026). "ADAM10-mediated cleavage of the Eph receptor ligand ephrin-B2 has been linked to fibrosis in pancreatic cancer, with radiation therapy shown to enhance ADAM10 expression on tumour cells and its cleavage of ephrin-B2 from stromal fibroblasts, thereby promoting tumour survival and fibrosis." (PMID 40427200, 2025).
arteriovenous malformations (4 papers, 2013 to 2025). "The animals exhibit arteriovenous malformations and also lack induction of arterial markers such as Ephrin B2." (PMID 34766259, 2022).
gastric cancer (4 papers, 2008 to 2022). A primary or metastatic malignant neoplasm involving the stomach. "Our data show a decreased phosphorylation of EFNB2 at Y306 in gastric cancer cells upon inhibition of CAMKK2." (PMID 35646067, 2022). "EFNB2 overexpression is reported in gastric cancer and its tyrosine phosphorylation promotes invasion of gastric cancer." (PMID 35646067, 2022). "EFNB2 is expressed abnormally high in multiple cancers, such as gastric cancer." (PMID 35646067, 2022). "Thus, patients with stage I, II, III, and IV stomach cancer have significantly higher overexpression of PYGB (p = 0.043), TNF (p = 0.02), HLA-A (0.05), and EFNB2 (0.001) genes, respectively." (PMID 33828156, 2021).